TNF (tumor necrosis factor)
Diseases named in the same sentence as TNF in open-access papers (continued):
Sharing a sentence is not in itself a finding about the gene and the disease.
Hypertension (continued). "In response to various stimuli such as infection, hypertension, and high glucose blood levels, brain endothelial cells produce free oxygen radicals and inflammatory cytokines, such as tumor necrosis factor-α (TNF-α)." (PMID 36768379, 2023). "Particularly in hypertension, TNF-a is upregulated and the use of its inhibitors has shown promising results in both experimental and clinical studies." (PMID 37529617, 2023). "Functional analysis indicated TNF-α involvement in hypertension and mediation of blood pressure and NaCl retention." (PMID 37627907, 2023). "Proinflammatory cytokines such as TNF have been shown to play a vital role in the pathogenesis of cardiovascular diseases, including hypertension." (PMID 36671012, 2023). "On the other hand, HIIT downregulated TNF-α and IL-6 and upregulated IL-10 expression, subsequently attenuating hypertension-induced inflammation." (PMID 36865350, 2023). "ROS promotes IL-6, TNF-α, and AT-1expression by activating NF-κB leading to hypertension and anxiety." (PMID 37273529, 2023). "But inhibition of TNF-α in multiple models of PE can attenuate hypertension, maternal inflammation, and fetal morbidity." (PMID 36909242, 2023). "Previously, it has been shown that IL-6 and TNF-α, positively correlated with blood pressure in pregnancy induced hypertension." (PMID 37745103, 2023). "The similar dependence of TNF-α and 8-iso-PgF2α on the grade of hypertension demonstrated the relationship between matrix stiffness and oxidative stress." (PMID 36674700, 2023). "Hypertension increases the T cell populations and inflammatory cytokine secretion of tumor necrosis factor TNFα, IFNγ, and IL-17A." (PMID 36839596, 2023). "Pro-inflammatory T cell aggravate hypertension by releasing pro-inflammatory cytokines, such as interleukin-17A (IL-17A) and TNF-α." (PMID 36925479, 2023). "Another study found significantly higher TNF-α in pregnancies complicated by hypertensive disorders one year postpartum." (PMID 37887854, 2023). "Several other inflammatory markers were identified as important in patients with obstructive sleep apnea and hypertension, including plasma monocyte chemoattractant protein-1, interleukin-1β, tumor necrosis factor-α, and interleukin-12." (PMID 35784707, 2022). "TNF-α (OR=1.007, P=0.025), IL-17 (OR=1.008, P=0.007), unemployed before surgery (OR=4.099, P=0.046), hypertension (OR=5.283, P=0.007), and CKD (OR=3.224, P=0.026) were associated with high risk of anxiety." (PMID 35239774, 2022). "Circulating levels of harmful proinflammatory cytokines, including interleukin-1β (IL-1β), interleukin-6 (IL-6), and tumor necrosis factor alpha (TNF-α) trigger to the development of hypertension and renal and cardiovascular disorders in humans." (PMID 36683859, 2022). "By downregulating the inflammatory markers including TNF-alpha and IL-β, naringin has prevented hypertension and ocular dysfunction." (PMID 36249455, 2022). "The pro-inflammatory cytokine TNF-α has been implicated in BP control in angiotensin II, Dahl salt-sensitive, DOCA-salt male rat models of hypertension, and male SHR." (PMID 35413930, 2022). "The increase of tumor necrosis factor-α (TNF-α) gene expression in PVAT under hypertension is related to the increase of ET-1 and endothelin receptors." (PMID 35295586, 2022). "The indicators of pro-inflammatory status (C-reactive protein, TNF-α, IL-6), corresponding to the normative range of values, were higher in males than in females both in uncomplicated hypertension and in the presence of HFpEF." (PMID 35997392, 2022). "We looked at TNF levels in the blood of 270 patients with coronary heart disease in the Chinese Hypertension League's Cholesterol and Recurrent Events (CARE) experiment to see if this notion held true." (PMID 35813433, 2022). "Studies have reported that chemokines (such as TNF-α and IL-6) are involved in the formation of hypertension." (PMID 35668772, 2022).
Hypertension (continued). "Despite data indicating TNF-α is a potent moderator of the processes governing hypertension development, the role of TNF-α in BP control in female SHR has not previously been examined." (PMID 35413930, 2022). "Vascular inflammatory mechanisms play an essential role in the development of hypertension and oxidative stress; thus, we investigated the expression of NF-kB and TNFα in MRA and aorta segments." (PMID 36139783, 2022). "Studies in which reduction or suppression of TNF inhibited the development of hypertension in mice in response to Ang II infusion, for instance, suggested that the inflammatory cytokine TNFα is involved in hypertension." (PMID 36685207, 2022). "For example, TNF-α influences hormone synthesis, placental architecture, and embryonic development in pregnancy; Pyridostigmine ameliorated hypertension and other PE-like symptoms in rat models of PE by inhibiting the synthesis of TNF-α." (PMID 36401313, 2022). "TNF-α is a well-established inflammatory cytokine in the acute phase response, whose expression has been shown to increase in human and rodent hypertension studies." (PMID 36703963, 2022). "As such, inflammation has been strongly documented in the pathophysiology of hypertension, and TNF-α has been identified as an important pro-inflammatory marker in hypertension." (PMID 36085061, 2022). "Further studies have shown that depletion of pro-inflammatory cytokines including interleukin-6 (IL-6) and tumor necrosis factor-alpha (TNF-α) ameliorates or prevents hypertension and related end-organ damage." (PMID 36620210, 2022). "TNF knockout attenuates Ang II-induced hypertension by reducing the expression of angiotensin-type 1 receptor." (PMID 35528518, 2022). "A positive correlation between 25(OH)D and TNF-α was also detected in pregnant women with hypertensive disorders." (PMID 36335311, 2022). "Monocytes from patients with essential hypertension are preactivated, producing greater amounts of IL-1β, TNF and IL-6 following ex vivo stimulation with angiotensin II or LPS than monocytes from healthy controls." (PMID 35743626, 2022). "Compared to females, males with essential hypertension complicated by HFpEF display significantly higher blood levels of pro-inflammatory autacoids: C-reactive protein, tumor necrosis factor alpha, and interleukin-6." (PMID 35997392, 2022). "The treatment of rats in preeclampsia with anti TNF-α antibodies attenuated hypertension and decreased IL-6 and sVCAM-1 levels." (PMID 33663436, 2021). "Sriramula S, Haque M, Majid DS, Francis J. Involvement of tumor necrosis factor-alpha in angiotensin II-mediated effects on salt appetite, hypertension, and cardiac hypertrophy." (PMID 33909773, 2021). "IL-6, TNF-α, and CRP can cause vascular endothelial dysfunction and participate in the occurrence of hypertension during pregnancy." (PMID 34790247, 2021). "The aorta mRNA relative expression levels of IL-6, TNF-α, NF-κB p65/Rela and NF-κB2 were significantly increased in the hypertension combined with HHcy group compared with the WKY group (p < 0.05)." (PMID 34603014, 2021). "Spontaneous hypertension also increased myocardial TNF-α, IFN-γ, and pro-fibrotic IL4, but decreased myocardial IL6 and IL10." (PMID 34368120, 2021). "The levels of pro‐inflammatory factors such as TNF‐α, IL‐1β and IL‐6 increase with the severity of hypertension, and affect its prognosis." (PMID 34331512, 2021). "Given the importance of the placenta in fetal nutrition, and considering that hypertension promotes low-grade inflammation, we analyzed placental TNF-α levels and confirmed the hypertensive pregnancy state by tail-cuff plethysmography." (PMID 34267676, 2021). "During hypertension, a low-grade inflammatory condition is established with the secretion of inflammatory cytokines, including TNF-α." (PMID 34267676, 2021).
Hypertension (continued). "All the pro-inflammatory biomarkers (IL-1β, IL-6, IL-8, and TNF-α) were positively correlated with the clinical parameters at baseline or following completed treatment, except for the PCR in subjects with hypertension." (PMID 34299815, 2021). "Lastly, we measured renal and splenic TNF in this study, a common inflammatory mediator involved in renal disease and hypertension." (PMID 33928103, 2021). "The results of our study confirmed positive correlations between systemic hypertension and plasma IL‐8, IL‐6 and TNF‐α levels in chronic CSC." (PMID 32701204, 2021). "Increased numbers of central memory CD8+ T cells, which can produce TNF, were found in patients with hypertension." (PMID 34055114, 2021). "What’s more, the aorta protein relative expression levels of IL-6 and TNF-α were also significantly increased in the hypertension combined with HHcy group compared with the WKY group (p < 0.05)." (PMID 34603014, 2021). "It was previously shown that the level of TNF-α is positively correlated with the degree of LVH in patients with hypertension." (PMID 33879070, 2021). "In this study, the expression of CD163 and CD206 in peripheral blood monocytes and the concentrations of IL-10 and TNF-α in the serum of patients with hypertension and healthy participants were detected." (PMID 33879070, 2021). "Ex vivo silencing of TIFA protein expression suppressed the secretion of IL-1β and TNF-α in PBMCs from patients with PAH or systemic hypertension." (PMID 34238983, 2021). "Potential confounding arose from higher rates of hypertension in the diabetic subgroups, again supporting potential benefit of TNF-α inhibitors in hypertension." (PMID 34698811, 2021). "This cytokine is majorly secreted by Th1 lymphocytes, and TNF-α is frequently involved in inflammatory and immunological processes occurring during arterial hypertension." (PMID 34267676, 2021). "It has been shown that neurogenic models of hypertension present increase reactive oxygen species, activation of NF-κB and production of TNF-α in the brain." (PMID 33967677, 2021). "It is worth noting that both IL-6 and TNF-α were increased in hypertension combined with HHcy rats, among which HHcy was the contributor for increased IL-6, while hypertension was the main factor for increased TNF-α." (PMID 34603014, 2021). "Plasma levels of IL-6 and TNF-α were also measured in a population of elderly subjects with hypertension undergoing aerobic training or aerobic and resistance training for 10 weeks." (PMID 32295038, 2020). "Tumor necrosis factor-α (TNF-α), above all, has been related to hypertension development and associated with the rate of renal injury." (PMID 32149110, 2020). "ICV administration of AZD8797, a CX3CR1 inhibitor, attenuates fructose-induced hypertension and expression of pro-inflammatory cytokines IL-1β, IL-6, and TNF-α." (PMID 32532282, 2020). "Hypertensive patients have higher circulating levels of the inflammatory cytokines IL-1β, IL-10, and tumor necrosis factor-alpha (TNF-α), indicating the potential use of these inflammatory biomarkers as markers for hypertension." (PMID 33265898, 2020). "Accordingly, the use of etanercept, a TNF-α antagonist, was able to inhibit vascular dysfunction and the hypertension induced by Ang-II." (PMID 32848763, 2020). "Conversely, Ang II-induced hypertension and cardiac hypertrophy were gradually aggravated, due to TNF-α-mediated intracellular signaling." (PMID 33324685, 2020). "We and others have previously demonstrated that serum levels of inflammatory cytokines, including TNF-α, which induces vasoconstriction and hypertension, are significantly elevated in the patients." (PMID 32878300, 2020). "Intrarenal TNF-α is increased by a high-salt diet in the Dahl Sal Sensitive (SS) rat, and administration of intrarenal etanercept increased SS hypertension and renal dysfunction." (PMID 32848763, 2020).
Hypertension (continued). "Again, the evidence indicates that production of proinflammatory cytokines, including TNF-α, IL-17, and IL-6, contribute to hypertension, likely by promoting vasoconstriction, production of reactive oxygen species, and sodium reabsorption in the kidney." (PMID 33218096, 2020). "It has been shown that the inflammatory cytokine tumor necrosis factor α (TNFα) plays a role in the development of hypertension and end-stage renal diseases." (PMID 32190663, 2020). "Inflammatory factors, such as C-reactive protein, IL-1β, IL-6, TNF-α, and ROS, are involved in the development and consolidation of hypertension by strengthening the stiffness of vessels and endothelial dysfunction." (PMID 33419373, 2020). "In summary, we showed that AZD8797, a CX3CR1 inhibitor, attenuated fructose-induced hypertension and expression of pro-inflammatory cytokines, IL-1β, IL-6, and TNF-α." (PMID 32532282, 2020). "Despite the role of chronic low-grade inflammation in hypertension, serum levels of PGRN and PGRN/TNF-α ratio and, their association with systolic and diastolic blood pressure has not been determined in hypertensive patients till now." (PMID 32424472, 2020). "When hypertensive stimuli persist, these effector memory T-cells infiltrate into the vasculature and the kidney and release cytokines like interferon gamma (INF-γ), interleukin-17 (IL-17), and tumor necrosis factor alpha (TNF-α), which aggravate hypertension." (PMID 33240096, 2020). "Blockade of TNFα has proven to have renal protective effects in various animal models of hypertension." (PMID 32190663, 2020). "Mercury-exposed citizens, especially those with hypertension, had significantly higher concentrations of inflammatory cytokines TNF-α, IL-2, IL-6 and anti-inflammatory cytokine IL-10 as compared to the unexposed population." (PMID 33083327, 2020). "It has been reported that blockade of TNFα with etanercept attenuates either hypertensive response or renal damage in various animal models of hypertension, including preeclampsia, angiotensin II-hypertensive rats, and a model of lupus erythematosus." (PMID 32190663, 2020). "The functional crosstalk between angiotensin II (Ang II) and tumor necrosis factor (TNF)-α has also been shown to cause adverse left ventricular remodeling and hypertrophy in hypertension." (PMID 32456629, 2020). "The levels of TNF-α, IL-2, IL-6 and IL-10 in serum were determined in mercury-exposed participants, suffering from hypertension." (PMID 33083327, 2020). "An increase of the IL-6 and TNF-α levels in the blood plasma was observed among the participants with hypertension in comparison with normotensive participants." (PMID 33083327, 2020). "We have previously shown that immune clearing of TNF‐α blunts Ang II‐induced hypertension in mice and that IFN‐γ‐deficient mice likewise develop blunted hypertension during Ang II infusion." (PMID 30414380, 2019). "In the present study, WEC significantly reduced the serum levels of CRP, TNF-α, IL-6, and sVCAM-1 in middle-aged and elderly subjects with overweight or prehypertension/mild hypertension." (PMID 31394768, 2019). "For future studies, it will be important to evaluate the chronic inhibition of the TNF-α and its implications, including side effects, in the context of hypertension." (PMID 31114507, 2019). "Our study further emphasizes a role of TH1‐like cytokines including IFN‐γ and TNF‐α in hypertension." (PMID 30414380, 2019). "Recently, we have shown that the percentage of both CD4+TNF+ and CD8+TNF+ T cells in perivascular adipose tissue was higher in Ang II–dependent hypertension in comparison with control animals." (PMID 31321561, 2019). "TNF-alpha in the kidney contributed to the development of hypertension and renal injury in Dahl salt-sensitive (SS) rats." (PMID 31321561, 2019). "While the pro-inflammatory cytokines such as IL-17, IFN-γ, and TNF-α have a detrimental effect in the pathogenesis of hypertension, the role of anti-inflammatory IL-10 is protective." (PMID 31321561, 2019).
Hypertension (continued). "The TNF-α levels of hypertension patients and normotensive group was highly significance (p<0.0001)." (PMID 31666827, 2019). "Since endothelial cells are related to the pathology of target tissue damage of hypertension, we used TNF‐α to induce the formation of EH mimics and examined changes about hsa_circ_0037909 and hsa‐miR‐637." (PMID 30861600, 2019). "Intrarenal TNF-α increased by high-salt diet in Dahl SS rats, and etanerecept administration improved renal damage and hypertension." (PMID 31321561, 2019). "Some studies also showed that the rats with CHF or hypertension had an increased level of TNFα or ROS in the PVN, resulting in the sympathoexcitation." (PMID 31391086, 2019). "Chemokines such as C-C motif chemokine ligand 2 (CCL2), and pro-inflammatory cytokines such as tumor necrosis factor alpha (TNF-α) and interleukin 1 beta (IL-1β), are upregulated both peripherally and centrally in hypertension." (PMID 31427987, 2019). "In angiotensin II-induced hypertension model, TNF-α plays a critical role and synergize with IL-17 to modulate inflammatory responses, resulting in an increase of vascular resistance which promotes hypertension and end-organ damage." (PMID 31803028, 2019). "TNF-α propagates renal damage during hypertension induced by activation of the renin–angiotensin system as well as exacerbates the severity of renal disease and poring overall outcomes and survival rates amongst the CKD patients." (PMID 30617956, 2019). "The primary study is done to reveal that the coronary endothelial dysfunction is separately associated with elevation of the plasma proinflammatory cytokines TNF-α in patients with hypertension." (PMID 31666827, 2019). "It is concluded that high blood pressure leads to generation of oxidative stress with remarkable elevation of TNF-α and malondialdehyde levels." (PMID 31666827, 2019). "Interaction effects of central obesity and hypertension with binary traits were found to affect TNF-α (Wald chi square = 10.1, P = 0.002) and adiponectin (Wald chi square = 10.3, P = 0.001)." (PMID 29636702, 2018). "Although serum AngII returns to its basal levels in the later stage of T. cruzi infection, renovascular-hypertension continues to inhibit TNF production." (PMID 29590257, 2018). "Our results showed that central obesity and hypertension interacted to affect circulatory concentration of adiponectin and TNF-α." (PMID 29636702, 2018). "Collectively, TNF-α induced hypertension and adverse cardiac remodeling via angiotensin II, were associated with changes in the MAPK/ TGF-β/NF-κB pathway." (PMID 29636702, 2018). "IP-10 was also associated with hypertension, and controls showed a significant correlation between frequency of CD4CD38HLDR+ and levels of IL-6, TNF-α, and IP-10." (PMID 29997625, 2018). "In hypertension, angiotensin II infusion stimulates T cells to produce TNF, and etanercept (TNF-α antagonist) blunts vascular superoxide production." (PMID 28891325, 2018). "Reports have demonstrated that various PICs such as TNF-α, IL-1β, and IL-6 play a vital role in the development of hypertension." (PMID 29573749, 2018). "Cross-talk between angiotensin II and pro-inflammatory adipokines (TNF-α) participates in self-amplifying and sustaining positive feedback loops, which results in the progression of hypertension and cardiac remodeling." (PMID 29636702, 2018). "A chronic increase in the production of pro-inflammatory cytokine, TNF-α, was found to induce hypertension in rats and stimulate the excessive secretion of sFlt-1, further supporting the effect of the immune system on inadequate angiogenesis in preeclampsia." (PMID 30079067, 2018). "Previous studies showed that TNF is elevated during hypertension in patients as well as in experimental models, and blockage of the TNF receptor prevents hypertension development in rats." (PMID 29590257, 2018).